AR (androgen receptor)
Diseases named in the same sentence as AR in open-access papers (continued):
Sharing a sentence is not in itself a finding about the gene and the disease.
prostate carcinoma (continued). "According to the McGill Androgen Receptor Mutation Database over 500 AR gene mutations have been identified in AIS as well as prostate cancer patients." (PMID 27110943, 2016). "We have previously demonstrated that sub-effective concentrations of an AR antagonist, bicalutamide, and the histone deacetylase inhibitor, vorinostat, act synergistically when combined to cause death of AR-dependent prostate cancer cells." (PMID 26907477, 2016). "Prostate cancers often become castration resistant due to alternative expression of androgen receptor (AR) splice variants." (PMID 27959342, 2016). "Such a model would provide a molecular framework for testing and exploring how the AR-interactome contributes to aberrant AR-dependent transcriptional programs underlying early and late stage prostate cancers." (PMID 27365400, 2016). "This has not only led to a better understanding of the mechanisms underlying AR activation in the progression of prostate cancer, but has also provided targets for new therapeutic interventions." (PMID 27363033, 2016). "Because of the cell cycle arrest and cell number reduction caused by BPAP, and because it is affecting AR levels, a major player in prostate cancer cell metabolism, we queried if BPAP was directly affecting mitochondrial activity and cell metabolism." (PMID 26918604, 2016). "Reciprocally, AR inhibition in PTEN-null prostate cancer caused AKT activation due to destabilization of the AKT phosphatase PHLPP, which resulted from reduced AR-targeted expression of FKBP5, a chaperone protein for PHLPP." (PMID 27557496, 2016). "The potential effect of type 3 AR variants on prostate cancer cell growth was assessed using LNCaP cells with stable heterologous expression of type 3a AR or type 3b AR." (PMID 28035996, 2016). "The AR is expressed in various tissues and has been linked to several diseases, most notably prostate cancer." (PMID 26880966, 2016). "Such unbiased sequencing approaches have the potential to identify all AR mutations arising in refractory prostate cancer patients provided the complete coding region is analyzed, but are unlikely to be used routinely in the near future." (PMID 26760770, 2016). "A therapeutical approach to combat hormone-naive prostate cancer is to treat patients with androgen antagonists, thus preventing the AR from activating genes associated with tumor growth and survival." (PMID 26559958, 2015). "The survival of a given prostate cancer cell is tightly linked to persistent AR signaling, and as such, these malignant cells will undergo a number of adaptive changes to ensure persistent AR signaling." (PMID 26566796, 2015). "To avoid potential confusion with the nomenclature of ARVs reported in human prostate cancer models, we named these three novel AR variants as mouse AR-Va, b, c (mAR-Va, b, c), of which mAR-Va was first identified in E8, with mAR-Vb and mAR-Vc in cE1." (PMID 26196517, 2015). "Prostate cancer progression to castration refractory disease is associated with anomalous transcriptional activity of the androgen receptor (AR) in an androgen-depleted milieu." (PMID 26036626, 2015). "Together, these data indicate that GDNF stimulation is associated with reduced RB activity and enhanced E2F1 and AR target gene expression in a subset of prostate carcinoma that are receptive to GDNF signaling by virtue of RET and/or GFRA1 receptor expression." (PMID 25575823, 2015). "Exposure to higher levels of androgens or overexpression/mutation of androgen receptor often leads to rapid proliferation of prostate cancer cells and, almost all the patients eventually relapse with tumors that become androgen-independent." (PMID 25690296, 2015). "There is rapidly increasing scientific evidence emphasizing on the fact that androgen depletion induced AR splice variants (ARVs) in prostate cancer cells to retain basal AR activity." (PMID 25705125, 2015).
prostate carcinoma (continued). "Interesting, a novel AR variant of similar structure was identified in several human prostate cancer cell lines." (PMID 26196517, 2015). "Their activity is partly dictated by the presence of androgen receptor mutations, which are commonly detected in patients who relapse while receiving antiandrogens, i.e. in castrate-resistant prostate cancer." (PMID 25693800, 2015). "In summary, this study showed that inhibition of AR activity caused increased activation of Wnt/β-catenin pathway and this increased activation promoted androgen-independent growth of prostate cancer cells." (PMID 26509262, 2015). "Prostate cancers (PCa) which progress due to gain of androgen receptor splice variants (ARv) or neuroendocrine features act independent of androgen signaling." (PMID 25605014, 2015). "The reported frequency of AR mutation in recurrent prostate cancer varies greatly between studies, ranging from 10–50%, but incidence does appear to correlate with therapy resistance." (PMID 25693800, 2015). "One key mutated gene in these pathways is EP300, a crucial gene for prostate cancer cell proliferation and hormone responsiveness of AR." (PMID 25915538, 2015). "Providing broader context relevant to AR signaling, several recent studies have provided lists of genes mutated at appreciable frequencies in sporadic prostate cancer, including castration resistant prostate cancer." (PMID 26485759, 2015). "Androgen receptor (AR) variants are associated with resistance to anti androgen therapy both in human prostate cancer cell lines and clinical samples." (PMID 26196517, 2015). "Our data shows that loss of LMTK2 protein is strongly associated with prostate cancer and prostate hyperplasia, disease states marked by dysregulation of AR." (PMID 26008968, 2015). "Progression of aggressive prostate cancers (PCa) with androgen receptor splice variants or neuroendrocrine features is currently untreatable in the clinic." (PMID 25605014, 2015). "Conversely, low AR in cancer stroma was associated with more extensive disease, and a greater risk of prostate cancer-related death (p<0.05)." (PMID 25965833, 2015). "The AR is a dihydrotestosterone (DHT) inducible nuclear hormone receptor whose transcriptional program has been implicated in the progression of prostate cancer." (PMID 26571387, 2015). "Etv1 directly interacts with the androgen receptor and drives the androgen receptor transcriptional response associated with aggressive prostate cancer." (PMID 25866208, 2015). "Herein, we highlight the emerging impacts of microRNAs and long non-coding RNAs linked to reactivation of the AR signaling axis and reprogramming of the cellular metabolism in prostate cancer." (PMID 26690121, 2015). "This protective AR-mediated phenotype in prostate cancer-associated stroma has implications for understanding the early stages of cancer progression, and for the use of androgen withdrawal in the absence of surgical management." (PMID 25965833, 2015). "Our study, for the first time, describes the natural occurrence of these AR NTD variants in Pten deficient mouse prostate cancer cells and the primary organ site." (PMID 26196517, 2015). "This Registered Report describes the proposed replication plan of key experiments from “Androgen Receptor Splice Variants Determine Taxane Sensitivity in Prostate Cancer” by Thadani-Mulero and colleagues (2014) published in Cancer Research in 2014." (PMID 26401448, 2015). "AR inhibitor resistance acquired in prostate cancer is associated with increased AR expression and PI3K/Akt activity." (PMID 26506516, 2015). "Longer poly-Q tracts tend to weaken AR activity and are associated with cryptorchidism, infertility and hypogonadism while shorter tract is associated with increased activation of the AR, which is linked to an increased risk of prostate cancer." (PMID 28031874, 2015).
prostate carcinoma (continued). "The altered gene expression in these adjunct tests can elucidate changes in the biology of prostate cancer, such as PCA3, which is associated with prostate cancer-cell survival and androgen receptor signaling." (PMID 26473288, 2015). "Coetzee and Ross showed for the first time that the variations of the length of the CAG are associated with prostate cancer and suggested that shorter alleles can lead to increased transactivation of androgen receptor." (PMID 26421011, 2015). "On the other hand, the anti-tumor effect of ectopically expressing TRPM8 in AR- prostate cancer xenograft is associated with decreased tumor neovascularization." (PMID 26512697, 2015). "Androgen receptor (AR) variants (AR-Vs) expressed in prostate cancer (PCa) lack the AR ligand binding domain (LBD) and function as constitutively active transcription factors." (PMID 25908785, 2015). "This is the first study to associate decreased stromal AR levels with increased prostate cancer-related death, even in the context of older patients with significant disease burden at the time of diagnosis and initial management." (PMID 25965833, 2015). "On the surface, this appears at odds with clinical data demonstrating an association between low stromal AR and death from prostate cancer." (PMID 25965833, 2015). "More recently, studies with human prostate cancer cell lines and tissues have identified the presence of AR splice variants (AR-Vs) which can be up-regulated in response to castration and promote resistance to androgen receptor targeted therapy." (PMID 26196517, 2015). "Accordingly, PCGEM1 and PRNCR1 were implicated in progression of prostate cancer (PCa) as transcriptional co-regulators of the androgen receptor (AR)." (PMID 25744782, 2015). "CK18 was recently detected in the circulation of patients with gastric and colorectal cancer, and linked to a particular subtype of prostate cancer that aberrantly expresses p63, lacks the androgen receptor (AR) and harbors rearrangements of the ERG gene." (PMID 25857301, 2015). "AR is also involved in several pathological situations, including genesis of prostatic hyperplasia and prostate cancer function or altered pubertal development due to its mutations." (PMID 25811655, 2015). "miR-205 negatively regulates AR and is associated with adverse the outcome of prostate cancer patients." (PMID 26314494, 2015). "Prostate cancers (PCa) that progress due to gain of androgen receptor splice variants (ARv) or neuroendocrine features act independent of androgen signaling." (PMID 25605014, 2015). "Stilbene and fluorinated dialkylaminostilbene (FIDAS) considerably inhibited AR activity in prostate cancer cells co-transfected with constitutively active ARΔLBD-variant Q640X and an AR-dependent reporter gene." (PMID 25705125, 2015). "Recently, it was also shown that the resistance of prostate cancer cells to the next-generation antiandrogen, enzalutamide, is due to increased expression of p52, which is mediated by aberrant AR activation and AR splice variant production." (PMID 26622945, 2015). "Treatment with bioactive ceramide also induces apoptosis in AR expressing LNCaP prostate cancer cells by causing nuclear fragmentation and activation of c-Jun N-terminal kinase (JNK), independent of PKC pathways." (PMID 26587537, 2015). "Cancer-associated dysfunctions of AR, such as aberrant activation due to mutations, amplification, splicing and cross talk with other pro-cancer signaling pathways contribute to prostate cancer (CaP) development and progression." (PMID 25883222, 2015). "In the current study of breast cancers, BNIP3 was highly expressed in the AR-positive group, which corresponded with a previous report of a significant association between BNIP3 expression and AR in prostate cancers." (PMID 25140630, 2014). "Mutations in the AR gene are rare in the early stages of prostate cancer, but their frequency increases significantly in advanced stages of the disease." (PMID 24659630, 2014).
prostate carcinoma (continued). "Androgen receptor (AR) signaling plays a seminal role in prostate development and homeostasis, and dysregulation of this pathway is intimately linked to prostate cancer pathogenesis and progression." (PMID 24681825, 2014). "In the altered pathway leading to prostate cancer, the androgen receptor displays an intriguing altered and mutational behavior, mostly treatment-induced." (PMID 25265995, 2014). "The second ASO sequence that we studied (A10) was designed to inhibit the production of the AR—a well-validated target associated with prostate cancer." (PMID 25398895, 2014). "Occasionally, prostate cancer cells exhibit a mutated AR, particularly in patients who are resistant to androgen ablation therapy." (PMID 24765197, 2014). "Over-activation of AR signaling is associated with progression of androgen-dependent prostate-cancers." (PMID 24971999, 2014). "In prostate cancer the PI3K/AKT pathway has been described as a key regulator in the transcription of the AR, and in breast cancer mutations at the PIK3CA gene were associated with expression of the AR in patients." (PMID 24779793, 2014). "Prostate cancer progression usually involves the shifting to an androgen-independent state, sometimes with mutation or loss of the androgen receptor (AR) and an increasing impact of growth factors signalling pathways 75,76." (PMID 24629090, 2014). "Repression of AR and Q640X-signalling by RSV and FIDAS in prostate cancer cells was caused by an inhibition of the AR and/or Q640X-dimerization." (PMID 24887556, 2014). "A link between the PI3K/mTOR pathway and AR signaling was previously established in prostate cancer and PIK3CA mutations are enriched in ER + breast cancer." (PMID 25103565, 2014). "Upregulation of constitutively-active androgen receptor splice variants (AR-Vs) has been implicated in AR-driven tumor progression in castration-resistant prostate cancer." (PMID 24722067, 2014). "We investigated the T877A-AR mutation, as it represents the most common AR mutation in clinical CaP specimens, and is the AR mutation found in the most studied prostatic cancer cell line, LNCaP." (PMID 25409505, 2014). "Increasing evidence suggests that C-terminal truncated AR splice variants play important roles in development of resistance to antiandrogen therapy in prostate cancer." (PMID 24508459, 2014). "Interaction between angiogenic endothelial cells and prostate cancer cells has also been reported to activate an IL-6/androgen receptor/TGFβ/gelatinase B/MMP-9 signal pathway that augments prostate cancer invasion in association with angiogenesis." (PMID 24473089, 2014). "In androgen-refractory prostate cancer, PRNBR1 and PCGEM1 are robustly expressed and are implicated in the ligand-independent activation of AR signaling [AR “resistant” prostate cancer]." (PMID 24723937, 2014). "To investigate this possibility, we first tested minoxidil in an AR transcription reporter assay using LNCaP prostate cancer cells, which harbor an endogenous AR with a T877A mutation." (PMID 24742982, 2014). "To evaluate tumor characteristics associated with response and resistance to AR pathway-directed therapy, we first determined intratumoral androgens and steroidogenic gene expression in two prostate cancer patient derived xenografts, LuCaP35 and LuCaP96." (PMID 25356728, 2014). "Dysregulated AR signaling is implicated in several types of tumor, including carcinomas of the prostate, breast, liver and bladder." (PMID 24397471, 2014). "It was reported that overexpression of ERBB2 activated AR pathway in prostate cancer cells in an androgen-deficient milieu." (PMID 24739220, 2014). "H2A.Z is also associated to androgen receptor (AR) gene transactivation and progression of prostate carcinoma (PCa)." (PMID 25003966, 2014). "In conclusion, the present study shows for the first time that shikonin treatment causes transcriptional repression of AR and inhibition of its nuclear localization in human prostate cancer cells." (PMID 24573652, 2014).
prostate carcinoma (continued). "The biological basis underlying the development of metastatic androgen-independent prostate cancer has been addressed, mainly focusing on AR over-expression, mutation, and cross-talk to other growth factor signaling pathways." (PMID 24618337, 2014). "A previous study showed that sarcosine increased both HER-2 mRNA and protein levels in an androgen-dependent prostate cancer cell line, suggesting an association among the androgen receptor, HER-2, and sarcosine." (PMID 24884785, 2014). "For example, aberrant phosphorylation, acetylation, methylation, sumoylation, and ubiquitination of the AR found in prostate cancer is caused by alterations of enzymes that modify the AR." (PMID 25988147, 2014). "The hinge domain null AR variants V2, V5, V7, and V4 are predominantly expressed in 22Rv1 prostate cancer cells." (PMID 24508459, 2014). "Prostate cancer (PCa) is the second leading cause of cancer related deaths in American men and elevated androgen receptor (AR) signaling facilitates PCa growth." (PMID 24466341, 2014). "Sequence variants in several genes, such as SRD5A (steroid-5-alpha-reductase alpha polypeptide), androgen receptor, estrogen receptor-β, E-cadherin, and toll-like receptors, have been associated with prostate cancer." (PMID 25045667, 2014). "These ‘engineered repressors’ are potent inhibitors of AR activity and prostate cancer cell growth and importantly inhibit the AR under circumstances in which conventional therapies would be predicted to fail, such as AR mutation and altered cofactor levels." (PMID 24659630, 2014). "AR mutations are more common in patients that have been treated for prostate cancer with anti-androgens." (PMID 24282788, 2013). "We identified miR-200b as a downstream target of androgen receptor and linked its expression to decreased tumorigenicity and metastatic capacity of the prostate cancer cells." (PMID 24391862, 2013). "This phenomenon indicates that anti-androgens sometimes stimulate prostate cancer cells for PSA production, and probably AR-mediated proliferation, causing selection pressure that induces prostate cancer that can grow on anti-androgen." (PMID 23896594, 2013). "We found that after adjusting for known risk factors in multivariate Cox regression models, AKR1C3 rs12529 and AR-CAG repeat length remained significantly associated with prostate cancer-specific mortality (PCSM) after ADT (P≤0.041)." (PMID 23359804, 2013). "ARs are expressed throughout prostate cancer progression and AR mutations, often found in hormone-refractory prostate cancers, allow AR-dependent transcriptional activity despite administration of targeted therapies designed to inhibit the receptor function." (PMID 23743823, 2013). "The monoallelic Androgen Receptor (AR) is associated with the onset, growth and development of Prostate cancer." (PMID 26877888, 2013). "It is also associated with prostate cancer cell growth in cell line studies, suggesting some significance of AR Serine 81 phosphorylation in AR function." (PMID 23945560, 2013). "We hope that this report will guide a similar search for AR mutations in prostate cancer patients who develop clinical resistance to enzalutamide." (PMID 23580326, 2013). "Since the LNCaP cell AR is mutated, we tested the effect of Casodex on LAPC4 prostate cancer cells, which have wild-type AR." (PMID 23363843, 2013). "More recently, an improved understanding of the underlying biology of prostate cancer has led to major clinical and translational advances, particularly in the development of novel androgen-ablative and AR antagonist strategies." (PMID 23152004, 2013). "Genomic, proteomic and metabolomic studies have implicated androgens/AR signaling in regulating metabolic processes in prostate cancer." (PMID 23405127, 2013).